SNORA3B (small nucleolar RNA, H/ACA box 3B)
Synonyms: ACA3-2; SNORA45; SNORA45B
Gene: Small nucleolar RNA gene on chromosome 11 (8,685,439 to 8,685,569, forward strand). Ensembl gene ENSG00000212607.
Gene Ontology:
Biological process: RNA processing
Cellular component: nucleolus
Homologues: Orthologues: chimpanzee SNORA3B (100% identical), macaque SNORA3B (98% identical), rat Snora3B (86% identical), mouse Gm24888 (83% identical). Paralogues in human: SNORA3C (85% identical), SNORA3A (66% identical).